ANO5 (anoctamin 5)
Description:
Plays a role in plasma membrane repair in a process involving annexins. Does not exhibit calcium-activated chloride channel (CaCC) activity.
Synonyms: GDD1; TMEM16E; LOC102723370; LGMD2L; LGMDR12
Tractability: Antibody: UniProt places it where antibodies can reach, with high confidence; its Gene Ontology location is reachable by antibodies, with high confidence; UniProt predicts a signal peptide or a membrane-spanning region. PROTAC: ubiquitination databases record sites on it.
Gene: Protein-coding gene on chromosome 11 (21,782,659 to 22,283,567, forward strand). Ensembl gene ENSG00000171714.
Subcellular location: Endoplasmic reticulum membrane; Cell membrane
Pathways (Reactome):
Disease: Induction of Cell-Cell Fusion
Hemostasis: Regulation of clotting cascade
Transport of small molecules: Stimuli-sensing channels
Gene Ontology:
Molecular function: intracellularly calcium-gated chloride channel activity; chloride channel activity; protein dimerization activity
Biological process: chloride transmembrane transport; plasma membrane repair; monoatomic ion transmembrane transport; phospholipid translocation
Cellular component: endoplasmic reticulum membrane; plasma membrane; vesicle
Genetic constraint (gnomAD): Loss-of-function variants: 89 observed, 102.71 expected, observed/expected ratio (o/e) 0.87, 90% interval 0.73 to 1.03. The upper end of that interval is the gene's LOEUF score, 1.03, which puts it in group 4 of 6, group 1 being the genes least tolerant of losing a copy. Missense variants: 987 observed, 1,050.1 expected, observed/expected ratio (o/e) 0.94, 90% interval 0.89 to 0.99. Synonymous variants: 382 observed, 357.48 expected, observed/expected ratio (o/e) 1.07, 90% interval 0.98 to 1.16.
Gene-disease validity (ClinGen):
ClinGen rates the evidence that ANO5 causes each of these diseases.
autosomal recessive limb-girdle muscular dystrophy (autosomal recessive): Definitive. Autosomal recessive form of limb-girdle muscular dystrophy.
gnathodiaphyseal dysplasia (autosomal dominant): Definitive. Gnathodiaphyseal dysplasia (GDD) is a bone dysplasia characterized by bone fragility, frequent bone fractures at a young age, cemento-osseous lesions of the jaw bones, bowing of tubular bones (tibia and fibula) and diaphyseal sclerosis of long bones associated with generalized osteopenia.
Homologues: Orthologues: chimpanzee ANO5 (99% identical), macaque ANO5 (97% identical), dog ANO5 (86% identical), guinea pig ANO5 (85% identical), pig ANO5 (83% identical), mouse Ano5 (80% identical), rabbit ANO5 (76% identical), rat Ano5 (76% identical), tropical clawed frog ano5 (62% identical), zebrafish ano5a (59% identical), zebrafish ano5b (58% identical). Paralogues in human: ANO6 (48% identical), ANO3 (41% identical), ANO4 (41% identical), ANO1 (38% identical), ANO2 (38% identical), ANO7 (34% identical), ANO9 (28% identical), ANO8 (22% identical), ANO10 (19% identical), PPP1R7 (9% identical).
Diseases named in the same sentence as ANO5 in open-access papers:
ANO5 is named in the same sentence as 68 diseases in open-access papers, as found by Europe PMC text mining. Sharing a sentence is not in itself a finding about the gene and the disease. The quoted sentences say what the papers report.
muscular dystrophy (25 papers, 2015 to 2025). Muscular dystrophy (MD) refers to a group of more than 30 genetic diseases characterized by progressive weakness and degeneration of the skeletal muscles that control movement. "In conclusion, we describe the first report of the ANO5:c.1770_1773del nonsense variant associated with mild muscular dystrophy." (PMID 39457424, 2024). "Along with ANO5, which has been connected to specific types of muscular dystrophy, ANO6 and ANO10 have also been linked to Scott syndrome and autosomal recessive spinocerebellar ataxia, respectively." (PMID 36836529, 2023). "Although ANO5-associated muscular dystrophies usually follow a recessive inheritance pattern, carriers can present milder phenotypes, with clinical signs limited to hyperCKemia." (PMID 35628876, 2022). "In the study presented herein, we address the mechanisms of clinical variability of ANO5-associated muscular dystrophies." (PMID 31395899, 2019). "Our data, in frame with other recent results, indicate that recessive ANO5 mutations are a frequent cause of muscular dystrophy and are population-specific." (PMID 31395899, 2019). "We recently showed that a LGMD2L patient carrying a frame-shifting mutation in ANO5 had truncated ANO5 expression, which is also prone to form intracellular aggregates, highlighting its potential contribution to the pathogenesis of muscular dystrophy." (PMID 29789544, 2018). "This novel ANO5 mutant rabbit model would be useful in studying the disease pathogenesis and therapeutic treatments for ANO5-deficient muscular dystrophy." (PMID 29789544, 2018). "Taken together, the ANO5 mutant rabbit model generated by CRISPR gene-editing recapitulates many aspects of muscular dystrophy associated with ANO5 mutations in human patients." (PMID 29789544, 2018). "Third, muscular dystrophy with mutations in ANO5 appears to be one of the most common adult muscular dystrophies in Northern Europe." (PMID 26693275, 2015). "In order to study the effect of ANO5 deficiency on skeletal muscle, we sought to examine the Ano5 KO mice for any signs of muscular dystrophy." (PMID 26693275, 2015). "ANO5 is the only member of this protein family associated with muscular dystrophy." (PMID 35563815, 2022). "This new model would facilitate the basic research to understand the pathogenesis of ANO5-associated muscular dystrophy and the physiological function of ANO5, and the translational studies to develop novel therapeutic strategies for the treatment of this disease." (PMID 29789544, 2018). "Elucidation of the genetic modifiers affecting muscular dystrophy associated with ANO5 mutations would not only shed light into the pathogenesis but may also offer us the opportunity to identify novel therapeutic targets to treat the disease." (PMID 29789544, 2018). "This novel ANO5-KO rabbit model could be used for pathogenesis studies and therapeutic development for ANO5-deficient muscular dystrophy." (PMID 29789544, 2018). "While ANO5-related muscular dystrophies have been relatively well researched, the molecular effects of ANO5 mutations on GDD are still unknown." (PMID 28176803, 2017). "Identifying such compensatory mechanisms could potentially lead to the development of novel therapies for ANO5-deficient muscular dystrophy." (PMID 26693275, 2015). "Interestingly, dominant mutations of ANO5 were reported to cause GDD1 in humans, but so far, only recessive mutations in ANO5 were reported to cause muscular dystrophy." (PMID 26693275, 2015). "Thus, defective PMR may also contribute to the development of muscular dystrophy caused by ANO5 mutations." (PMID 34963485, 2021). "Thus, this raises a possibility that genetic modifiers may also contribute to the disease manifestation in muscular dystrophy associated with ANO5 mutations." (PMID 29789544, 2018).
muscular dystrophy (continued). "It is not very clear what exactly underlies the pathological variations in these ANO5-KO mice, however, the nature and localization of the mutations and the species difference are most likely responsible for the poor modeling of ANO5-deficient muscular dystrophy in mice." (PMID 29789544, 2018). "The differentially expressed genes included several causative genes of congenital heart defects, hypertrophic cardiomyopathy, congenital long-QT syndrome, muscular dystrophy, and dilated cardiomyopathy (e.g., Acta2, Ankrd1, Scn4b, Ano5, Rpl3l, Cenpf)." (PMID 35942699, 2022). "ANO5 muscular dystrophies have a high prevalence in northern European populations, which is likely due to a founder mutation." (PMID 36292621, 2022). "The Ano5-mutant rabbits developed clear signs of muscular dystrophy with increased serum CK levels, muscle necrosis, regeneration, fatty replacement, and fibrosis starting from 12 months of age." (PMID 33584832, 2021). "We present the first human muscle cell model to examine the cellular function of ANO5 in muscular dystrophy." (PMID 31341644, 2019). "The ANO5-/- rabbits displayed typical muscular dystrophy signs as evidenced by scattered necrotic muscle fibers with inflammatory infiltrates." (PMID 29789544, 2018). "Genetic defects in ANO5 were identified to be responsible for two types of autosomal recessive muscular dystrophies." (PMID 26693275, 2015). "Ano5 deficient mice exhibited little pathology in skeletal muscle while others reported a mild muscular dystrophy phenotype in a different strain of Ano5-KO mice, which also exhibited defective myoblast fusion and delayed muscle regeneration after cardiotoxin injection." (PMID 34963485, 2021). "Further, these studies show that ER helps injured cells cope with Ca2+ overload during PMR, lack of which contributes to muscular dystrophy due to mutations in the ANO5 protein." (PMID 33987529, 2021). "However, an ANO5 gene trapped mouse model with the insertion in intron 8 showed residual expression of mutant ANO5 transcript and presented with a mild muscular dystrophy phenotype." (PMID 29789544, 2018). "On this evidence, ANO5 dimer dysfunction may be specific not only for GDD mutation, but also for the pathologic activity in case of muscular dystrophy mutations." (PMID 27216912, 2016). "These ANO5 mutations spread across the gene, indicating the absence of mutation hot spots in muscular dystrophy patients." (PMID 27216912, 2016). "The results presented in this study demonstrates that genetic ablation of Ano5 in C57BL6/J mice does not recapitulate ANO5-deficient muscular dystrophy and associated cardiomyopathy as in human patients." (PMID 26693275, 2015). "Our data demonstrates that complete disruption of Ano5 expression in mice does not recapitulate the ANO5-deficient muscular dystrophy seen in human patients." (PMID 26693275, 2015). "Furthermore, GDD mutations are mainly concentrated within exon 11 of ANO5, causing osteoblastic dysfunction, while other mutations cause muscular dystrophy, mostly without a bone phenotype." (PMID 40861765, 2025). "Most of muscular dystrophy mutations are frameshift, or caused by truncation of the protein, or splice site changes, and thus mutant ANO5 protein could not form functional dimer structures." (PMID 27216912, 2016). "Muscle cells from patients and mouse model for the muscular dystrophy showed that lack of Anoctamin 5 (ANO5)/Transmembrane protein 16E (TMEM16E), an ER-resident putative Ca2+-activated chloride channel (CaCC), are poor at coping with cytosolic Ca2+ overload." (PMID 33987529, 2021). "Two independent lines of mice with complete disruption of ANO5 transcripts did not exhibit overt muscular dystrophy phenotypes; instead, one of these mice was observed to present with some abnormality in sperm motility." (PMID 29789544, 2018). "The lack of muscular dystrophy phenotype in our Ano5 KO mice is in sharp contrast to what has been reported in clinical studies." (PMID 26693275, 2015).
muscular dystrophy (continued). "The Ano5 KO mice did not display any obvious signs of muscular dystrophy as examined by various established methods." (PMID 26693275, 2015). "To date, pathophysiology of ANO5-related muscular dystrophies is largely unknown and disease-specific treatments do not exist." (PMID 35563815, 2022). "To test whether the lack of muscular dystrophy phenotype in the Ano5 KO mice might be due to the upregulation of other anoctamin genes, we compared the expression of all nine other anoctamin genes in skeletal muscle between WT and KO mice by quantitative RT-PCR." (PMID 26693275, 2015).
gnathodiaphyseal dysplasia (22 papers, 2014 to 2026). "In summary, our investigation identified a novel pathogenic variant in the ANO5, responsible for gnathodiaphyseal dysplasia in a large Iranian family." (PMID 35758145, 2022). "Mutations in ANO5 were first implicated in patients with an autosomal dominant skeletal dysplastic syndrome, gnathodiaphyseal dysplasia (GDD), in 2004." (PMID 36292621, 2022). "ANO5 is involved in skeletomuscular function; its mutations cause gnathodiaphyseal dysplasia, an autosomal dominant inherited bone disorder." (PMID 35207044, 2022). "ANO5/TMEM16E gene mutations also result in the autosomal dominant bone disorder gnathodiaphyseal dysplasia (GDD)." (PMID 31341644, 2019). "ANO5 (TMEM16E) is now known for its role in myoblast proliferation and muscle repair, while gain of function mutations of ANO5 cause gnathodiaphyseal dysplasia." (PMID 30893776, 2019). "Recessive mutations in ANO5 cause severe myopathies like gnathodiaphyseal dysplasia, GDD45,46, limb-girdle muscular dystrophy type-2L, LGMD2L47, and Miyoshi muscular dystrophy-3, MMD347,48." (PMID 30631052, 2019). "Mutations in ANO5 are associated with gnathodiaphyseal dysplasia (GDD), a skeletal disorder causing the jaw deformity and long bone fractures." (PMID 35982081, 2022). "Mutations in the human TMEM16E (ANO5) gene are associated both with the bone disease gnathodiaphyseal dysplasia (GDD; OMIM: 166260) and muscle dystrophies (OMIM: 611307, 613319)." (PMID 29124309, 2018). "Furthermore, autosomal dominant mutations in ANO5 at this locus have been identified in patients with gnathodiaphyseal dysplasia (GDD) and are considered a potential causative agent, suggesting a genetic association between FGC and GDD." (PMID 37649308, 2023). "Genetic mutations in the ANO5 gene cause recessive LGMDR12 and Miyoshi myopathy type 3 (MMD3) characterized by progressive muscle weakness and degeneration, and dominant gnathodiaphyseal dysplasia (GDD)." (PMID 34963485, 2021). "Mutations in the anoctamin-5 (ANO5) gene can lead to musculoskeletal disorders, with monoallelic (autosomal dominant) mutations typically presenting as skeletal abnormalities known as gnathodiaphyseal dysplasia (GDD)." (PMID 40067389, 2025). "TMEM16E/ANO5 (initially named GDD1) is responsible for gnathodiaphyseal dysplasia, and does not exhibit cell surface Ca2+-activated Cl- channel activity." (PMID 29444117, 2018).
limb-girdle muscular dystrophy (10 papers, 2012 to 2024). Limb-girdle muscular dystrophy (LGMD) is a heterogeneous group of muscular dystrophies characterized by proximal weakness affecting the pelvic and shoulder girdles. "First, variants in MLXIPL and ANO5 were found to cause extreme quantitative traits in hyperuricemia and limb-girdle muscular dystrophy, respectively." (PMID 38584274, 2024). "Limb-girdle muscular dystrophy was diagnosed in one patient after identifying two likely causal variants in ANO5 gene, but common mitochondrial variant m.11778G > A associated with LHON was also identified." (PMID 37784170, 2023). "Here we report on two unrelated adult patients presenting with Limb girdle muscular dystrophy who were found to have novel variants in ANO5." (PMID 35463132, 2022). "A broad phenotypic spectrum of limb girdle muscular dystrophy (LGMD2L) is caused by frameshift or point mutations in ANO5." (PMID 28176803, 2017). "Recently, recessive mutations in the anoctamin 5 (ANO5) gene were identified as the cause of predominantly asymmetric limb-girdle muscular dystrophy (LGMD type 2L) as well as distal myopathies of the MM phenotype (MMD3)." (PMID 23050857, 2012). "ANO5 variants have been previously linked to several types of myopathies including limb-girdle muscular dystrophy type 2L (LGMD), with symptoms that include severely elevated serum CK." (PMID 38584274, 2024). "We studied 786 undiagnosed patients with LGMD or nonspecific myopathic features to investigate the role of ANO5 mutations in limb-girdle muscular dystrophies (LGMDs) and in nonspecific myopathies using the next generation sequencing (NGS) approach." (PMID 25891276, 2015). "LGMD2L is a subtype of limb-girdle muscular dystrophy (LGMD), caused by recessive mutations in ANO5, encoding anoctamin-5 (ANO5)." (PMID 31395899, 2019).
limb girdle muscular dystrophy type 2L (7 papers, 2012 to 2024). "Mutations in the anoctamin 5 gene have been assigned to limb-girdle muscular dystrophy type 2L, while distal Miyoshi-like phenotypes have been classified as Miyoshi myopathy type 3." (PMID 23050857, 2012). "Limb girdle muscular dystrophy type 2L (LGMD2L) and Miyoshi myopathy type 3 (MMD3) are autosomal recessive muscular dystrophy caused by mutations in the gene encoding anoctamin-5 (ANO5), which belongs to the anoctamin protein family." (PMID 29789544, 2018).
Miyoshi myopathy (7 papers, 2014 to 2022). A distal myopathy, characterized by weakness in the distal lower extremity posterior compartment (gastrocnemius and soleus muscles) and associated with difficulties in standing on tip toes. "Other potentially deleterious missense mutations in LD with ALT-increasing alleles were found in ANO5, which is associated with Miyoshi muscular dystrophy; the breast/ovarian cancer susceptibility gene BRCA1; and LRBA, associated with common variable immunodeficiency." (PMID 33547301, 2021). "Autosomal recessive mutations in Anoctamin 5 (ANO5/TMEM16E), a member of the transmembrane 16 (TMEM16) family of Ca2+-activated ion channels and phospholipid scramblases, cause adult-onset muscular dystrophies (limb girdle muscular dystrophy 2L (LGMD2L) and Miyoshi Muscular Dystrophy (MMD3)." (PMID 31341644, 2019). "Recently, recessive mutations in the anoctamin 5 gene (ANO5) were identified as a cause of LGMD2L and non-dysferlin Miyoshi myopathy." (PMID 25135358, 2014). "In conclusion, we suggest that the terms “anoctaminopathy” or “ANO5 myopathy” better define a heterogeneous disease caused by mutations in the ANO5 gene, irrespective of the first proximal (LGMD2L), distal symptoms (Miyoshi myopathy) or characterized by other myopathic features." (PMID 25891276, 2015).
Miyoshi muscular dystrophy 3 (6 papers, 2019 to 2024). "Loss-of-function variants in ANO5 cause autosomal recessive muscular diseases of Miyoshi muscular dystrophy 3 (MMD3) or limb–girdle muscular dystrophy 12 (LGMDR12)." (PMID 39457424, 2024). "ANO5: One patient (7/A), presenting with myalgia, cramps, and proximal weakness with areflexia, carried two pathogenic variants in ANO5 (Miyoshi-3 muscular dystrophy, OMIM*608662)." (PMID 37510298, 2023). "Mutations in ANO5 with recessive inheritance occur in proximal LGMD2L and Miyoshi muscular dystrophy 3 (MMD3)." (PMID 33567613, 2021).
dysferlinopathies (5 papers, 2015 to 2022). "Interestingly, it was demonstrated that ANO5 is involved in a sarcolemmal repairing mechanism similar to dysferlin, in which its defects give rise to muscle diseases (dysferlinopathy), resembling anoctaminopathy-5." (PMID 36292621, 2022). "Phenotypic similarities between ANO5-myopathies and dysferlinopathies, lead to hypothesize that ANO5 may function in membrane repair comparable to DYSF." (PMID 34067866, 2021). "This was demonstrated in a mouse model of dysferlinopathy, where the overexpression of human ANO5 did not rescue the myopathy phenotype or ameliorate the sarcolemmal repair defect." (PMID 36292621, 2022).
distal myopathies (4 papers, 2012 to 2024). "Mutations in the anoctamin 5 gene have so far been identified only in some cases of limb-girdle and distal myopathy." (PMID 23050857, 2012). "The recommended molecular approach for establishing the diagnosis of distal myopathies, including ANO5 muscle disease, generally includes a multigene panel or comprehensive genomic testing, with exome sequencing being more common than genome sequencing." (PMID 39457424, 2024). "Recessive mutations in ANO5 are clinically presented by three phenotypes: limb-girdle muscular dystrophy type 2L (LGMD2L), Miyoshi-like distal myopathy (MMD3) and increased serum creatine kinase with variable exercise intolerance." (PMID 37510237, 2023). "Therefore, given the increasing number of anoctamin 5 mutations in Miyoshi-like phenotypes, genetic analysis should include an anoctamin 5 screen in late-onset limb-girdle and distal myopathies." (PMID 23050857, 2012).